MIR516A2 (microRNA 516a-2)
Synonyms: hsa-mir-516-2; hsa-mir-516a-2; MIRN516-2; MIRN516A-2; MIRN516A2; mir-516a-2
Gene: MicroRNA gene on chromosome 19 (53,761,133 to 53,761,222, forward strand). Ensembl gene ENSG00000207620.
Gene Ontology:
Biological process: miRNA-mediated post-transcriptional gene silencing
Homologues: Orthologues: chimpanzee ptr-mir-516a-2 (100% identical), macaque mml-mir-516a-1 (91% identical). Paralogues in human: MIR516A1 (99% identical), MIR516B1 (91% identical), MIR520C (88% identical), MIR518E (86% identical), MIR519C (86% identical), MIR518C (84% identical), MIR519A2 (84% identical), MIR520F (84% identical), MIR522 (84% identical), MIR518D (83% identical), MIR520E (83% identical), MIR523 (83% identical), and 12 more.